LRP2 (LDL receptor related protein 2)
Diseases named in the same sentence as LRP2 in open-access papers (continued):
Sharing a sentence is not in itself a finding about the gene and the disease.
osteoporosis (1 paper, 2011). A condition of reduced bone mass, with decreased cortical thickness and a decrease in the number and size of the trabeculae of cancellous bone (but normal chemical composition), resulting in increased fracture incidence. "In 2007, Hsu and colleague firstly suggested that LRP2 is one of two potential osteoporosis candidate genes in chromosome 2q quantitative trait loci (QTL) region in a Chinese population." (PMID 22174918, 2011). "This negative result indicates that LRP2 is not the major contributor of osteoporosis." (PMID 22174918, 2011).
periodontitis (1 paper, 2025). An acute or chronic inflammatory process that affects the tissues that surround and support the teeth. "In addition, in the LR, LRP2, and LRP5 groups, lower levels of TNF-α and IL-1β were observed in both tissue and serum samples, similar to the finding that TNF-α and IL-1β levels were correlated with the degree of periodontitis and decreased after SRP." (PMID 39941567, 2025).
prostate adenocarcinoma (1 paper, 2023). "In The Cancer Genome Atlas Prostate Adenocarcinoma (TCGA-PRAD, Firehose Version) cohort, LRP2 was also lower in areas of tumor, but not further lower by Gleason grade." (PMID 36875158, 2023).
renal carcinoma (1 paper, 2020). A carcinoma arising from the epithelium of the renal parenchyma or the renal pelvis. "We sorted PTECs from the normal renal cortex of two patients with renal cancer by FACS and further confirmed their identify by LRP2 gene expression." (PMID 33184300, 2020).
respiratory failure (1 paper, 2016). The significant impairment of gas exchange within the lungs resulting in hypoxia, hypercarbia, or both, to the extent that organ tissue perfusion is severely compromised. "The small number of Lrp2 knockout mice that survive until birth experience severe vitamin D3 deficiency, as the reabsorption of vitamin D and the vitamin D binding protein from the kidney proximal tubule is LRP2-dependant, but die of respiratory failure." (PMID 26949399, 2016).
retinoblastoma (1 paper, 2025). A malignant tumor that originates in the nuclear layer of the retina. "However, in retinoblastoma (GSE208143), LRP2 was downregulated, while CUBN, CAV1, GIPC1, and DAB2IP were upregulated." (PMID 41374987, 2025).
selenium deficiency (1 paper, 2023). A nutritional deficiency disease resulting from inadequate selenium levels in the body, which can lead to impaired function of selenoproteins essential for antioxidant defense and thyroid hormone metabolism. "In selenium deficiency, the “alphabet” selenoproteins are affected hierarchically, both with respect to the particular selenoprotein and the tissue of expression, as the brain or endocrine glands are hardly affected by Se deficiency due to their equipment with LRP2 or LRP8." (PMID 37958974, 2023).
skin cancer (1 paper, 2020). "LRP2 can increase the proliferation of neural precursor cells in the subependymal zone and the proliferation and survival of skin cancer cells, however, it is unclear whether cells of the OL lineage express LRP2, or whether Lrp1 deletion could alter LRP2 expression." (PMID 33282858, 2020).
squamous intraepithelial lesions (1 paper, 2024). "Furthermore, research has demonstrated that LRP2 is overexpressed in high-grade squamous intraepithelial lesions (HSIL) compared with low-grade squamous intraepithelial lesions (LSIL)." (PMID 39346724, 2024).
Strabismus (1 paper, 2021). A misalignment of the eyes so that the visual axes deviate from bifoveal fixation. "Nevertheless, it is unknown whether the strabismus exhibited in these patients is a primary phenotype caused by LRP2 deficiency or merely a secondary change from abnormal development and function of the brain and/or ocular organs." (PMID 34872573, 2021). "In additional, neither strabismus was observed in these LRP2-deficient models (mouse and zebrafish)." (PMID 34872573, 2021).
thyroid tumor (1 paper, 2022). A benign or malignant neoplasm affecting the thyroid gland. "In thyroid tumors, LRP2 mediated the suppressive effect of metformin on cancer proliferation by blocking JNK signaling." (PMID 35975176, 2022).
uveal melanoma (1 paper, 2025). A melanoma derived from melanocytes of the uveal tract. "Incorporating LRP2, CUBN, Caveolin-1, GIPC1, and DAB2IP into biomarker-driven clinical trial design could enhance risk stratification in uveal melanoma and RB and support the development of prognostic signatures that distinguish aggressive from indolent disease." (PMID 41374987, 2025). "To evaluate the prognostic relevance of LRP2, CUBN, DAB2IP, GIPC1, and CAV1 in uveal melanoma, we performed overall survival analysis using the GEPIA2 online platform." (PMID 41374987, 2025).
cancer (25 papers, 2014 to 2025). A tumor composed of atypical neoplastic, often pleomorphic cells that invade other tissues. "We further observed that LRP2 downregulation was associated with dedifferentiated tumor subsets in multiple cancer types." (PMID 36980716, 2023). "Overall, this explorative analysis of the TCGA dataset is consistent with a model where epigenetic silencing of LRP2 is associated with tumor dedifferentiation and poor patient outcome in multiple cancer types arising from LRP2-expressing absorptive epithelia." (PMID 36980716, 2023). "To characterize the mechanisms that lead to putative loss of LRP2 expression in some tumors, we next explored the mutation profile of LRP2 in human cancers." (PMID 36980716, 2023). "In patients with congenital pulmonary airway malformation, functional destructive mutations of LRP2 were also found to be highly relevant in lung development and cancer." (PMID 36851274, 2023). "In a pan-cancer analysis, the results suggested that LRP2 mutations were associated with high immune cell infiltration, immune checkpoint gene expression and high enrichment of immune-related signaling pathways." (PMID 35834061, 2022). "Survival analysis revealed two methylation sites localised at the CDH17 and LRP2 genes, respectively, to be able to predict risk of cancer recurrence." (PMID 36612154, 2022). "Similar to the pan-cancer analysis, LRP2 mutations had high TMB, MSI and immune cell infiltration in EC and also leaded to high expression of immune-related genes, such as CXCL9, CXCR6, CXCL13, ICOS and immune checkpoint genes (CTLA4 and LAG3)." (PMID 35834061, 2022). "Meanwhile, we demonstrated the association of LMS score with LRP2 mutation signature, survival status and genes expression in EC and pan-cancer cohort." (PMID 35834061, 2022). "We investigated the characteristics of low-density lipoprotein receptor-related protein 2 (LRP2) mutation in the cancer genome atlas (TCGA) and explored the potential association of LRP2 mutations with immunotherapy." (PMID 35834061, 2022). "The aim of this study is to evaluate the value of LRP2 mutations in predicating cancer immunotherapy." (PMID 35834061, 2022). "Furthermore, loss of LRP2 expression was associated with dedifferentiated histological and molecular subtypes of these cancers." (PMID 36980716, 2023). "However, we also highlight that a subset of tumors within these cancer types show epigenetic silencing of LRP2, which is associated with tumor dedifferentiation and poor survival." (PMID 36980716, 2023). "Interestingly, low LRP2 expression was associated with tumor cell dedifferentiation and poorer patient outcome, suggesting LRP2 is a potential cancer biomarker." (PMID 36980716, 2023). "In the context of cancer, loss of LRP2 protein could alter the cellular uptake and clearance of ligands from the tumor microenvironment." (PMID 36980716, 2023). "Altered LRP2 expression and/or mutations have been described in various cancers, including CC." (PMID 36612154, 2022). "Then, we evaluated the impact of LRP2 mutations on prognosis in pan-cancer analysis." (PMID 35834061, 2022). "Characteristics of LRP2 mutations in 33 cancer types were analyzed using large-scale public data." (PMID 35834061, 2022). "We identified 797 LRP2-mutated patients in 32 cancer types (7.28%)." (PMID 35834061, 2022). "We analyzed LRP2 mutations in whole exome sequences from 10,953 patients with 32 cancer types." (PMID 35834061, 2022). "We believed that this paper may lead to the development of diagnostic and therapeutic tools based on a better understanding of LRP2 mutations in cancer." (PMID 35834061, 2022). "In addition, LRP2 was reported to relate to fibrosis-associated diseases and cancer through the TGF-β pathway." (PMID 35975176, 2022). "Therefore, we hypothesized that epigenetic events could account for loss of LRP2 expression in cancer." (PMID 36980716, 2023).
cancer (continued). "LRP2 encodes a low-density lipoprotein receptor-related protein-2 which mediates endocytic uptake of various lipids, and is linked to the enhanced metabolism of lipids and vitamin D, and promotes the transformation, proliferation and survival of various types of cancer cells." (PMID 31754644, 2019). "The simultaneous knockdown of CD320 and LRP2 is necessary to inhibit cancer cell growth, indicating the presence of other pathways involved in VB12 uptake." (PMID 40565117, 2025). "Accordingly, we suggest that future cancer-type-specific studies should investigate further the potential of LRP2 as an independent prognostic biomarker." (PMID 36980716, 2023). "To investigate the clinical and molecular correlates of LRP2 expression across human cancers, we performed an integrated analysis of publicly available data from The Cancer Genome Atlas." (PMID 36980716, 2023). "On the other hand, the correlation is modest within tumor types that express mid-to-low levels of LRP2, including LUAD and SKCM, suggesting that other factors contribute to differential LRP2 expression in these cancer types." (PMID 36980716, 2023). "In the present study, we examine the gene expression of LRP2 across 33 cancer types in The Cancer Genome Atlas." (PMID 36980716, 2023). "As expected, we found the highest LRP2 expression in cancers arising from LRP2-expressing epithelia." (PMID 36980716, 2023). "Based on these analyses, we considered a framework where LRP2 expression is generally maintained in the cancer setting, but where its expression is lost in a subset of tumors, and that this is associated with poor patient outcome." (PMID 36980716, 2023). "As expected, the highest levels of LRP2 were found in cancer types that arise from LRP2-expressing absorptive epithelial cells." (PMID 36980716, 2023). "Based on the observation that a subset of tumors within these cancer types showed lower LRP2 expression, we stratified samples into LRP2high or LRP2low based on a lower quartile cutoff and performed Kaplan–Meier analysis." (PMID 36980716, 2023). "Instead, our data support a model where LRP2 is maintained in cancers arising from absorptive epithelial cells known to express high levels of LRP2 in the healthy state." (PMID 36980716, 2023). "LRP2 expression was variable across cancer types with the highest expression in cancers arising from tissues known to express LRP2 in the healthy state." (PMID 36980716, 2023). "We find that LRP2 expression is largely restricted to cancer types that arise from LRP2-expressing absorptive epithelia." (PMID 36980716, 2023). "To do so, we performed univariate Cox proportional-hazards modelling of LRP2 expression and survival within individual TCGA cancer types." (PMID 36980716, 2023). "In publicly available cohorts, LRP2 expression was also lower in areas of cancer and further decreased by Gleason." (PMID 36875158, 2023). "To characterize the expression of LRP2 across human cancers, we accessed RNA sequencing data from TCGA, consisting of 10,534 samples across 33 cancer types." (PMID 36980716, 2023). "A subset of tumors within these cancer types show downregulation of LRP2, which is correlated with epigenetic alterations in the LRP2 gene locus, tumor dedifferentiation, and poor patient outcome." (PMID 36980716, 2023). "To further explore the relationship between LRP2 expression and cg02361027 methylation, we calculated their correlation within individual cancer types." (PMID 36980716, 2023). "LRP2/megalin was one of the first endocytic cargos identified for the Dab2 adaptor and has been found related to poor prognosis in various cancer." (PMID 35975176, 2022). "In the pan-cancer cohort, these results showed significant differences between TMB and various LRP2 mutation types (truncating mutant, missense mutant and multiple mutations)." (PMID 35834061, 2022). "Here, we examined the expression of LRP2 across 33 cancer types in The Cancer Genome Atlas." (PMID 36980716, 2023).
cancer (continued). "Putative tumor-suppressive functions of LRP2 could be exerted through the clearance of ligands that modulate proliferation, migration, and survival of cancer cells." (PMID 36980716, 2023). "However, the results presented in the current study are correlative, and future studies are needed to dissect the exact mechanisms of LRP2 regulation in cancer." (PMID 36980716, 2023). "Investigation of LRP2 levels across cancer types showed considerable variation in LRP2 expression within individual cancer types, which could suggest that LRP2 is deregulated in a subset of tumors." (PMID 36980716, 2023). "Our data also highlight deregulation of LRP2 as a common event in these cancer types." (PMID 36980716, 2023). "In this study, we found that LRP2 mutations were not statistically association with prognosis in most TCGA cancer types." (PMID 35834061, 2022). "Megalin (encoded by LRP2/Lrp2) was proposed as a putative RSHBG in renal tubules and cancer cells." (PMID 30626909, 2019). "Therefore, we examined LRP2 expression across 33 cancer types in The Cancer Genome Atlas." (PMID 36980716, 2023). "Given that more than 40 ligands have been identified for LRP2 to date, we hypothesize that multiple tissue-, context- and ligand-dependent cellular signaling pathways would be impacted by downregulation of this receptor in cancer cells." (PMID 36980716, 2023). "Finally, the findings presented here might also have implications for the use of LRP2 as a target for anti-cancer drug delivery." (PMID 36980716, 2023). "However, in a subset of tumors from these cancer types, we observed epigenetic silencing of LRP2." (PMID 36980716, 2023). "A pan-cancer study found that LRP2 mutations were linked with increased immune cell infiltration, immune checkpoint gene expression, and significant enrichment of immune-related signaling pathways, as well as a better prognosis, compared to individuals who did not have LRP2 mutations." (PMID 38455474, 2024). "By contrast, cancers without a strong baseline epithelial LRP2 can aberrantly gain Megalin and exploit its functions." (PMID 41374987, 2025). "Loss-of-function mutations and gene deletions in LRP2 are rare and cannot not explain the extent of lost LRP2 expression observed across cancer types." (PMID 36980716, 2023). "Similar to the results of the pan-cancer analysis, LRP2 mutations in ECs also presented higher infiltration of CD8 T cell, plasma cells, and M1 macrophages than those without LRP2 mutations." (PMID 35834061, 2022). "In both ECs and pan-cancer data, LRP2 mutations exhibited higher LMS score than those without LRP2 mutations." (PMID 35834061, 2022). "However, our pan-cancer analysis did not immediately reveal other cancer types with gained expression of LRP2." (PMID 36980716, 2023). "However, the role and regulation of LRP2 in cancers that arise from these tissues has not been delineated." (PMID 36980716, 2023). "In addition, targeted drugs against LRP2 and NKAIN4 may also improve the immune tolerance of cancer cells, thereby reducing the proliferation, invasion and migration capabilities of cancer cells, and improving the prognosis of patients." (PMID 36727052, 2022). "By analyzing a previously published ChIP-seq dataset that profiled genome-wide SREBP2 binding in the HCC70 human carcinoma epithelial cell line, we found that SREBP2 binding is enriched at the promoter and the intron 1 of the BMP2 gene as well as in the promoter of the LRP2 gene." (PMID 35833708, 2022). "Co-occurring of genetic mutations in cancers with KDM5C alterations were not uncommon in both early-stage and advanced stage cohort and some of them are prevalent driver genes (e.g., LRP2, KMT2C, PBRM1, NOTCH1, FAT1, SETD2, NSD1, etc.), while their clinical significance remained undetermined." (PMID 33953726, 2021).